ARHGAP8 (Rho GTPase activating protein 8)
Description:
GTPase activator for the Rho-type GTPases by converting them to an inactive GDP-bound state.
Synonyms: FLJ20185; BPGAP1; PP610
Tractability: PROTAC: ubiquitination databases record sites on it.
Gene: Protein-coding gene on chromosome 22 (44,752,547 to 44,862,788, forward strand). Ensembl gene ENSG00000241484.
Pathways (Reactome):
Signal Transduction: RHOA GTPase cycle
Gene Ontology:
Molecular function: GTPase activator activity; protein binding
Biological process: positive regulation of ERK1 and ERK2 cascade; negative regulation of endocytic recycling; regulation of small GTPase mediated signal transduction; small GTPase-mediated signal transduction; signal transduction
Cellular component: cytoplasm; cytosol
Genetic constraint (gnomAD): Loss-of-function variants: 60 observed, 45.1 expected, observed/expected ratio (o/e) 1.33, 90% interval 1.08 to 1.65. The synonymous counts are far from expectation, so gnomAD's model fits this gene poorly and the ratio says little. Missense variants: 890 observed, 554.71 expected, observed/expected ratio (o/e) 1.6, 90% interval 1.52 to 1.7. Synonymous variants: 369 observed, 243.01 expected, observed/expected ratio (o/e) 1.52, 90% interval 1.39 to 1.65.
Homologues: Orthologues: chimpanzee ARHGAP8 (99% identical), macaque ARHGAP8 (95% identical), dog ARHGAP8 (83% identical), pig ARHGAP8 (82% identical), mouse Arhgap8 (79% identical), guinea pig ARHGAP8 (77% identical), rat Arhgap8 (74% identical). Paralogues in human: ARHGAP1 (51% identical).
Diseases named in the same sentence as ARHGAP8 in open-access papers:
ARHGAP8 is named in the same sentence as 19 diseases in open-access papers, as found by Europe PMC text mining. Sharing a sentence is not in itself a finding about the gene and the disease. The quoted sentences say what the papers report.
breast carcinoma (3 papers, 2017 to 2023). "Germline mutations in ARHGAP8 have been identified in colorectal and breast cancers." (PMID 36291758, 2022).
bipolar disorder (2 papers, 2018 to 2026). A disorder of the brain that causes unusual shifts in mood, energy, activity levels and the ability to carry out day-to-day tasks. "Notably, prior GWAS findings have also linked ARHGAP8 to binge eating behavior in bipolar disorder, further implicating it in neuropsychiatric behavioral regulation." (PMID 41168987, 2026).
Obesity (2 papers, 2018 to 2023). Accumulation of substantial excess body fat. "In addition, PAS-SNPs have also been identified in other obesity-related genes: Abcc6 and Npc1 in the Fat line and Lsamp (limbic system-associated membrane protein) in the Lean line, as well as in Arhgap8 (Rho GTPase activating protein 8) in the Fat line, which is localised in the dominant Fob2." (PMID 36414820, 2023).
Bladder cancer (1 paper, 2023). "Similarly, ARHGAP8 is overexpressed in most colorectal cancers compared to normal tissues, but we observe relatively low expression in Bladder cancer, suggesting that ARHGAP8 may play different roles in different tumors, but its role in osteosarcoma is unknown." (PMID 38041020, 2023).
cervical cancer (1 paper, 2022). A primary or metastatic malignant neoplasm involving the cervix. "The ARHGAP8 gene was found to be overexpressed in colon cancer tissue vs. adjacent normal colon tissue in association with cervical cancer invasiveness." (PMID 36291758, 2022).
Constipation (1 paper, 2015). Infrequent or difficult evacuation of feces. "Of the ten up-regulated genes, the largest decrease in the transcripts of constipation rats was observed for Serpina3n (0.19-fold), followed Lcn2, Slc5a8, C3, Rerg, and Arhgap8." (PMID 26151867, 2015).
tumor (6 papers, 2010 to 2023). "A higher ARHGAP8 correlated both with lower Th1/Th2 cell ratio and lower M1 macrophage infiltration, which indicated a tumor-promoting microenvironment and lower DC cell infiltration, which contributed to a tumor suppression microenvironment." (PMID 34307347, 2021). "Five hypermethylated loci harbored by four genes (GSTP1, TACSTD2, BMP4 and RASSF1) and three hypomethylated loci in three genes (ARHGAP8, GPR35 and DLGAP1) were validated using 7 assays with 12 tumor-normal tissue pairs from this study." (PMID 23437062, 2013). "Although the function of ARHGAP8 and ARHGEFG is unknown, ARHGAP8 is thought to inhibit the Rho-signaling pathway; hence reduced expression of ARHGAP8 may also results in Rhomediated tumor invasion." (PMID 21119890, 2010).
cancer (3 papers, 2020 to 2025). A tumor composed of atypical neoplastic, often pleomorphic cells that invade other tissues. "ARHGAP8, or BPGAP1, is a RhoGAP protein linked to cancer progression." (PMID 41465326, 2025).
ARHGAP8 also shares sentences with these, for which no sentence is quoted: gastric cancer (2 papers); breast tumor (1); colon cancer (1); colorectal cancer (1); colorectal tumors (1); epilepsy (1); ischemic stroke (1); osteosarcoma (1); schizophrenia (1); stomach adenocarcinoma (1); stomach cancers (1).